HSD17B7 (hydroxysteroid 17-beta dehydrogenase 7)
Description:
Bifunctional enzyme involved in steroid-hormone metabolism and cholesterol biosynthesis. Catalyzes the NADP(H)-dependent reduction of estrogens and androgens and regulates the biological potency of these steroids. Converts estrone (E1) to a more potent estrogen, 17beta-estradiol (E2). Converts dihydrotestosterone (DHT) to its inactive form 5a-androstane-3b,17b-diol. Converts moderately progesterone to 3beta-hydroxypregn-4-ene-20-one, leading to its inactivation. Additionally, participates in the post-squalene cholesterol biosynthesis, as a 3-ketosteroid reductase. [Isoform 3]: Does not have enzymatic activities toward E1 and DHT.
Synonyms: SDR37C1; PRAP
Tractability: Small molecule: a high-quality ligand is known; it belongs to a druggable protein family. Antibody: UniProt predicts a signal peptide or a membrane-spanning region. PROTAC: ubiquitination databases record sites on it; its protein half-life has been measured; a small molecule that binds it is known.
Target class: Enzyme; Oxidoreductase
Gene: Protein-coding gene on chromosome 1 (162,790,702 to 162,812,823, forward strand). Ensembl gene ENSG00000132196.
Subcellular location: Endoplasmic reticulum membrane
Pathways (Reactome):
Metabolism: Cholesterol biosynthesis via desmosterol (Bloch pathway); Zymostenol biosynthesis via lathosterol (Kandutsch-Russell pathway)
Gene Ontology:
Molecular function: 3-beta-hydroxysteroid 3-dehydrogenase (NADP+) activity; 5-alpha-androstane-3-beta,17-beta-diol dehydrogenase (NADP+) activity; estradiol 17-beta-dehydrogenase [NAD(P)+] activity
Biological process: androgen metabolic process; cholesterol biosynthetic process; estrogen biosynthetic process; brain development; embryonic organ development; steroid biosynthetic process; zymosterol biosynthetic process
Cellular component: endoplasmic reticulum membrane; mitochondrion; endoplasmic reticulum
Genetic constraint (gnomAD): Loss-of-function variants: 15 observed, 25.06 expected, observed/expected ratio (o/e) 0.6, 90% interval 0.4 to 0.92. The upper end of that interval is the gene's LOEUF score, 0.92, which puts it in group 3 of 6, group 1 being the genes least tolerant of losing a copy. Missense variants: 217 observed, 308.92 expected, observed/expected ratio (o/e) 0.7, 90% interval 0.63 to 0.79. Synonymous variants: 99 observed, 121.04 expected, observed/expected ratio (o/e) 0.82, 90% interval 0.69 to 0.97.
Homologues: Orthologues: chimpanzee HSD17B7 (99% identical), macaque HSD17B7 (97% identical), guinea pig HSD17B7 (84% identical), pig HSD17B7 (84% identical), dog HSD17B7 (81% identical), rat Hsd17b7 (80% identical), mouse Hsd17b7 (77% identical), tropical clawed frog hsd17b7 (63% identical), zebrafish hsd17b7 (58% identical). Paralogues in human: WWOX (19% identical), RDH16 (19% identical), HSD17B1 (19% identical), SDR16C5 (19% identical), HSD17B6 (18% identical), RDH12 (18% identical), RDH5 (18% identical), HSD11B2 (18% identical), DHRS9 (18% identical), RDH11 (18% identical), HSD17B2 (18% identical), BDH1 (17% identical), and 13 more.
Diseases named in the same sentence as HSD17B7 in open-access papers:
HSD17B7 is named in the same sentence as 28 diseases in open-access papers, as found by Europe PMC text mining. Sharing a sentence is not in itself a finding about the gene and the disease. The quoted sentences say what the papers report.
breast carcinoma (6 papers, 2012 to 2024). "Studies have shown that the HSD17B7 gene is highly expressed in breast cancer cells, causing the progression of breast cancer." (PMID 38791004, 2024). "The stimulation of HSD17B7 expression by estradiol provides a powerful feed-forward mechanism for estradiol biosynthesis in breast cancer cells." (PMID 23216862, 2012). "Knocking down HSD17B7 expression in breast cancer cell lines resulted in a marked reduction in proliferation, suggesting it may be a potential target for treatment of ERα-positive breast cancer." (PMID 28430630, 2017). "In this study, using TCGA data, HSD17B7, ACADL, ME1, MAOA, and TDO2 were identified as the top five DEGs related to FA metabolism in breast cancer tissues." (PMID 36936412, 2023). "On the contrary, increased expression of E2 HSD17B-synthetizing enzymes HSD17B1, HSD17B7 and HSD17B5 correlates with better ER+ breast cancer patient outcome for RFS and/or DMFS." (PMID 36674737, 2023). "In our study, E2 treatment significantly increased the expression of HSD17B7 in lipedema ASCs but not in healthy cells, suggesting a role of estradiol in lipedema pathogenesis similar to breast cancer." (PMID 38791004, 2024). "These were Estrogen Biosynthesis (HSD17B7 and HSD17B12), Estrogen-Dependent Breast Cancer Signaling (HSD17B7 and HSD17B12), Hepatic Fibrosis/Hepatic Stellate Activation (CD14 and CD40), Tight Junction Signaling (CDSF1 and OCLN), and Dopamine-DARPP32 Feedback in cAMP Signaling (CACNAID and CSNK1E)." (PMID 23759029, 2013).
arteriosclerosis (1 paper, 2020). A vascular disorder characterized by thickening and hardening of the walls of the arteries. "Presence of arteriosclerosis associated significantly with expression of SQLE, FDPS, MVD, HMGCS1, HSD17B7 and HSF1 (all p≤0.05)." (PMID 32353828, 2020).
cyst (1 paper, 2022). A sac-like closed membranous structure that may be empty or contain fluid or amorphous material. "Therefore, we speculated decreasing HSD17B7 expression in bovine cyst follicles hindered the synthesis of steroid hormones in follicles and could not convert E1 to E2." (PMID 36311668, 2022).
gastric cancer (1 paper, 2023). A primary or metastatic malignant neoplasm involving the stomach. "In other studies, the overexpression of HSD17B7 was related to the progression of gastric cancer and the poor prognosis of renal cancer." (PMID 36674737, 2023).
hearing loss (1 paper, 2026). "Together, our findings suggest a conserved and essential role for HSD17B7-mediated cholesterol biosynthesis in sensory hair cell function and identify HSD17B7 as a candidate gene for sensorineural hearing loss." (PMID 42233258, 2026).
osteoporosis (1 paper, 2026). A condition of reduced bone mass, with decreased cortical thickness and a decrease in the number and size of the trabeculae of cancellous bone (but normal chemical composition), resulting in increased fracture incidence. "Therefore, HSD17B7 regulation is a novel therapeutic approach for alleviating estrogen-deficient osteoporosis." (PMID 41631094, 2026). "Additionally, in preosteoclasts derived from patients with severe osteoporosis, the expression of HSD17B7 and ERα was significantly reduced compared to the control subjects." (PMID 41631094, 2026).
ovarian carcinoma (1 paper, 2023). A malignant neoplasm originating from the surface ovarian epithelium. "In addition, high intratumoural mRNA levels of the enzyme HSD17B7, which increases E2 levels, are associated with increased OS in ovarian cancer patients (HR = 0.83 (0.72–0.94), p = 0.0052)." (PMID 36674737, 2023).
prostate carcinoma (1 paper, 2021). A carcinoma that arises from epithelial cells of the prostate gland. "Consistent with an involvement of ETS transcription factors in control of HSD17B7 expression, this gene is part of transcriptional network described in ETV1‐overexpressing prostate cancer cells." (PMID 34185380, 2021).
psoriasis (1 paper, 2022). An autoimmune condition characterized by red, well-delineated plaques with silvery scales that are usually on the extensor surfaces and scalp. "However, there is not enough evidence for CFDP1, TRAPPC9, HSD17B7, and KIAA0415’s effects on psoriasis and neutrophils." (PMID 36569916, 2022).
sarcopenia (1 paper, 2026). Progressive decline in muscle mass due to aging which results in decreased functional capacity of muscles. "Thus, DECR1, HSD17B7 (AUC > 0.85), and OPN3 (AUC > 0.85) may serve as strong diagnostic biomarkers for sarcopenia." (PMID 41460756, 2026).
viral infection (1 paper, 2024). "The results revealed that the suppression of SQLE and HSD17B7 expression, which occurred either 6 h before or after viral infection, led to a significant reduction in viral replication." (PMID 39872814, 2024).
vitamin D deficiency (1 paper, 2017). A nutritional condition produced by a deficiency of VITAMIN D in the diet, insufficient production of vitamin D in the skin, inadequate absorption of vitamin D from the diet, or abnormal conversion of vitamin D to its bioactive metabolites. "Importantly, five key enzymes in the consecutive enzymatic reactions in steroid biosynthesis, including Lss, Cyp51, Tm7sf2, Nsdhl, and Hsd17b7, were downregulated, indicating a possible mechanism for vitamin D deficiency in NAFLD." (PMID 28179399, 2017).
cancer (8 papers, 2018 to 2023). A tumor composed of atypical neoplastic, often pleomorphic cells that invade other tissues. "While HSD17B7‐dependent zymosterol and cholesterol production can therefore have a direct impact on mitochondria, they could also function as part of a bidirectional mitocellular communication network, which has also been implicated in cancer disparities among populations with different ancestries." (PMID 34185380, 2021). "Significantly, five of these genes (Mvd, Sqle, Cyp51, Hsd17b7, and Dhcr24) are within the core biochemical processes of the mevalonate pathway, an important target for anti-cancer therapy." (PMID 32477466, 2020). "ACSL3, AIFM2, HSD17B7, LPCAT1, LSS, PLIN3 and RAB10 were up-regulated with the progression of cancer stage of HCC patients, while CIDEB, G0S2, HSD17B13, PLIN1 and PLIN2 were down-regulated." (PMID 37464334, 2023). "Importantly, we observed an inverse correlation between circulating HDL-c and transcript levels of Phgdh and five enzymes of the mevalonate pathway (Mvd, Sqle, Cyp51, Hsd17b7, and Dhcr24) in tumor bed, suggestive of an inhibitory role for apoA-I/HDL in cancer cell metabolism." (PMID 32477466, 2020).
infection (2 papers, 2011 to 2025). The state of being infected such as from the introduction of a foreign agent such as serum, vaccine, antigenic substance or organism. "We used lentiviral infection followed by clonal selection with plasmids for RNAi knockdown of Hsd17b7 to create cell lines with reduced levels of Hsd17b7 (approx. 80% reduced, data not shown) and then treated the lines with recombinant SHH, as done with the MEFs." (PMID 21912524, 2011).
tumor (2 papers, 2020 to 2021). "In the Th17 lineage, RORC (receptor) is upregulated on the tumor infiltrating CD4+ T-cells and its ligands (CYP51A1, FDFT1, HSD17B7, LBR, TM7SF2, MSMO1, NSDHL) are also upregulated on the tumor cells, implying GBM expresses ligands that induces Th17 phenotype in tumor infiltrating helper T-cell." (PMID 34012510, 2021).
metabolic disease (1 paper, 2020). A congenital disorder (due to inherited enzyme abnormality) or acquired (due to failure of a metabolically important organ) disorder resulting from an abnormal metabolic process. "Arsg and Hsd17b7, which are expressed at higher levels in NZO livers were linked to the GO-Term metabolic processes and might participate in metabolic diseases." (PMID 32350386, 2020).
HSD17B7 also shares sentences with these, for which no sentence is quoted: Obesity (2 papers); Azoospermia (1); Bardet-Biedl syndrome (1); colon cancer (1); colorectal cancer (1); Hepatic fibrosis (1); Huntington disease (1); Hypercholesterolemia (1); hypogonadism (1); hypospadias (1); Noonan syndrome (1); renal carcinoma (1).